JAM3 (junctional adhesion molecule 3)
Diseases named in the same sentence as JAM3 in open-access papers (continued):
Sharing a sentence is not in itself a finding about the gene and the disease.
tumor (continued). "JAM3 suppresses KYSE410 cell xenograft tumor growth in vivo." (PMID 36461092, 2022). "In the tumors overexpressing RBPJ+/+ Mφ-Exo tumors were significantly smaller than all other tumors, therefore the upregulation of hsa_circ_0004658, which leads to the downregulation of miR-499b-5p and the upregulation of JAM3, results in a tumor-suppressive phenotype in the mouse HCC model." (PMID 35013102, 2022). "In addition to JAM3, opposing roles in promoting and suppressing tumor growth have been reported for the same molecules in different cell type of cancers." (PMID 36461092, 2022). "Moreover, RBPJ+/+ Mφ-Exo inhibits tumor growth by upregulating the hsa_circ_0004658/miR-499b-5p/JAM3 pathway in vivo." (PMID 35013102, 2022). "Our results agree with those suggesting that JAM3 acts as a tumor suppressor." (PMID 35013102, 2022). "In the first pathway, PDX1 could upregulate target gene JAM3 to promote the cell immune response and inhibit tumor cell growth." (PMID 31126066, 2019). "Next, ligand IL2 (a T cell differentiation signaling) binds to receptor IL2RC to trigger target gene JAM3, which could promote cell immune response and inhibit tumor cell growth." (PMID 31126066, 2019). "Tumor methylation data were used to build a methylation signature of PTEN loss in our cohort, which was confirmed in TCGA, and included CpGs in ATP11A, GDNF, JAK1, JAM3, and VAPA." (PMID 29137428, 2017). "Notably, JAM3, which participates in cell-cell adhesion, and may also be utilized by cancer cells to promote tumour progression or survival, showed not only hypermethylation but also copy number loss accompanied by under-expression." (PMID 25137136, 2014). "Many signals favoring tumor cells were significantly activated in C2, such as integrin-related signals (COL9A3 − (ITGA2+ITGB1), JAM3 − (ITGAM+ITGB2), COL6A1 − (ITGA1+ITGB1)), immune suppression signals (CD99 − PILRA), etc.." (PMID 39391717, 2024). "The tumor weight was 0.252 ± 0.030 g and 0.027 ± 0.010 g in JAM3 unexpressed KYSE410 cell xenografts and in JAM3 re-expressed KYSE410 cell xenografts." (PMID 36461092, 2022). "Transcriptional profiles of circulating tumour cells from 5 different cancer types revealed conserved upregulation of PECAM‐1, JAM3 (JAM‐C) and F11R (JAM‐A), which are critical for leucocyte diapedesis." (PMID 33210465, 2020). "The JAM3 protein was located in the cytoplasm, as identified by homogeneous yellow staining, and positively expressed in normal bile duct cells, but low or negatively expressed in most CCA tumour cells." (PMID 38124399, 2024). "Hypermethylation of JAM3 was frequently observed in CCA tissues, and the methylation status of CpG island sites was significantly related to the expression level of JAM3 mRNA or protein in CCA cell lines and tumour tissues." (PMID 38124399, 2024). "Additionally, we showed that JAM3 was negatively correlated with anti-tumor immune cells such as CD8+ T cells, while positively correlated with pro-tumor immune cells such as M2 macrophages, suggesting its involvement in immune cell infiltration." (PMID 38400838, 2024).
cancer (24 papers, 2008 to 2025). A tumor composed of atypical neoplastic, often pleomorphic cells that invade other tissues. "Environmental factors were regarded as major causes of aberrant epigenetic changes in human cancer, explaining the phenomenon of JAM3 methylation with family history." (PMID 36461092, 2022). "JAM3 is a junctional adhesion molecule that has been implicated in several cancers." (PMID 35013102, 2022). "These cells leverage F11R/JAM1‐mediated intercellular junctions through JAM3 interactions with cancer and stromal cells, potentially establishing physical exclusion zones that limit immunocyte infiltration." (PMID 41057994, 2025). "In our investigation, we found JAM3 to be an independent prognostic factor for BC, although its role in cancer is debated." (PMID 38400838, 2024). "The expression profile, role and mechanism of JAM3 vary according to cancer type, and in some cases, are even paradoxical." (PMID 38124399, 2024). "Although the expression of JAM3 has been reported previously in different human cancers, its biological role remains controversial." (PMID 38124399, 2024). "Even though JAM3 was reported to be involved in different cancers, its role in cancer initiation and development is still in controversial." (PMID 36461092, 2022). "JAM3 is highly expressed in adjacent tissue samples and reduced in primary cancer samples (p < 0.01), and JAM3 is mainly located in the cell membrane and cytoplasm." (PMID 36461092, 2022). "The expression of JAM3 promotes metastasis by enhancing both the adhesion of cancer cells to extracellular matrices and the subsequent invasion." (PMID 32979257, 2020). "More recently, hypermethylation of JAM3 has been reported in certain types of cancer." (PMID 38124399, 2024). "Junctional adhesion molecule 3 (JAM3) can be used as a prognostic marker in multiple cancer types." (PMID 37115068, 2023). "The role and the mechanism of JAM3 are different in various cancers." (PMID 36461092, 2022). "In HCC and matched para-carcinoma tissues, the expression of JAM3 was downregulated in HCC." (PMID 35013102, 2022). "Importantly, myCAFs might take advantage of F11R (also called JAM1, junctional adhesion molecule 1) to form tight junctions with cancer and stromal cells through F11R and JAM3, which might prevent the infiltration of immunocytes." (PMID 35986392, 2022). "Therefore, PAX1/JAM3 methylation detection could not only reduce the number of patients who were missed or misdiagnosed by cytology, but also offers a highly sensitive marker panel for cancer, especially those unrelated to HPV infection." (PMID 39659794, 2024). "The presented study confirmed the sarcoid-specific increase in the expression of not only the JAM3 gene, but also the ITGB1 gene, whose expression is considered to be a poor outcome marker during cancer prognosis." (PMID 35742950, 2022). "In turn, the JAM3 protein, which regulates cells adhesion and communication between cells and ECM, is up-regulated in variety of cancers." (PMID 35742950, 2022). "In GC, there is only one study reporting higher JAM3 expression in cancer tissues compared to healthy controls, and no studies on its related functions or effector mechanisms has been published yet." (PMID 35768842, 2022). "Focal adhesion, PI3K-Akt signaling pathway, Proteoglycans in cancer, ECM-receptor interaction, Protein digestion and absorption, cGMP-PKG signaling route, TGF-beta signaling pathway, and many more were found to be enriched for in the JAM3 Kyoto encyclopedia of genes and genomes pathway." (PMID 37115068, 2023). "Interactions between junctional adhesion molecules (JAMs), including F11R, JAM2, and JAM3, are identified, and while their role during AV development is unknown, they are essential drivers of EMT in the context of cancer metastasis, modulating morphology, migration, and cell polarity." (PMID 37689753, 2023).
infection (13 papers, 2011 to 2025). The state of being infected such as from the introduction of a foreign agent such as serum, vaccine, antigenic substance or organism. "Barrier functions genes such as CLDN1 (Claudin 1) and JAM3 (Junctional Adhesion Molecule 3) were significantly upregulated in response to infection in both jejunum and caecum." (PMID 40500794, 2025). "The genes specifically downregulated over the course of infection by Fasciola miRNAs included Nod1, E2f1, Tnfaip3 and Cdk6 at 6 hrs, and Jam3, Vegfa, Nod1, Uvrag and Nlrc3 at 18 hrs." (PMID 39344634, 2024). "At 10 d PI, the JAM3 mRNA levels were significantly affected by both infection (P = 0.0381) and feed (P = 0.0006)." (PMID 33652244, 2021). "JAM3 and PAX1 methylation have statistical significance with HPV sustained infection lasting more than 3 years compared to less than 3 years." (PMID 38611108, 2024). "Taking methylated JAM3 and PAX1 as another biomarker of sustained infection is a new finding in this study, suggesting that this group of women may progress more rapidly to precancerous lesions, which is worthy of clinical study." (PMID 38611108, 2024).
adenocarcinoma (3 papers, 2024 to 2026). A common cancer characterized by the presence of malignant glandular cells. "Specifically, these two cases exhibited notably high levels of PAX1 and JAM3 methylation (Patient 1: ΔCtPAX1 = 2.52, ΔCtJAM3 = 5.28, LBC: NILM; Patient 2: ΔCtPAX1 = 1.82, ΔCtJAM3 = 3.72, LBC: adenocarcinoma)." (PMID 39659794, 2024). "Notably, two cases of adenocarcinoma in this study, which were negative for hrHPV and had normal cytological results, exhibited high methylation levels of both PAX1 and JAM3." (PMID 41239544, 2026).
genetic disorder (1 paper, 2025). "In addition, at least one other rare genetic disorder (involving JAM3) produces a similar “pseudo-TORCH” pattern." (PMID 40937018, 2025).
JAM3 also shares sentences with these, for which no sentence is quoted: acute pancreatitis (6 papers); pancreatitis (6); breast carcinoma (4); peritonitis (4); rheumatoid arthritis (4); Arthritis (3); atherosclerosis (3); acute myeloid leukemia (2); age-related macular degeneration (2); fibrosarcoma (2); ischemia (2); ischemia reperfusion injury (2); lung carcinoma (2); lymph node metastasis (2); osteoarthritis (2); ovarian tumor (2); rhabdomyosarcoma (2); Thrombocytopenia (2); acute kidney injury (1); acute lung injury (1); acute respiratory distress syndrome (1); allergic contact dermatitis (1); brain diseases (1); cholangitis (1); cholelithiasis (1); chronic lung disease (1); congenital hydrocephalus (1); COVID-19 (1); diabetes (1); Failure to thrive (1).
A further 40 diseases each share a sentence with JAM3 in 1 paper.